SOX7 (SRY-box transcription factor 7)
Diseases named in the same sentence as SOX7 in open-access papers (continued):
Sharing a sentence is not in itself a finding about the gene and the disease.
glioma (10 papers, 2017 to 2025). A benign or malignant brain and spinal cord tumor that arises from glial cells (astrocytes, oligodendrocytes, ependymal cells). "The formed NBAT1/miR-21/SOX7 axis represents the underlying molecular mechanism of NBAT1 functions in glioma." (PMID 37047365, 2023). "NC, sh-AB073614, or AB073614 lentiviral vector was transduced into U251 cells to further investigate the association of AB073614 with SOX7 expression in glioma." (PMID 29029454, 2017). "SOX7 inhibits the proliferation of glioma, renal cell carcinoma, colorectal cancer and acute leukemia." (PMID 39889187, 2025). "LncRNA AB073614 induces the activity of the Wnt/β-catenin signaling pathway by downregulating the SOX7 expression and promoting the progression of glioma." (PMID 37047365, 2023). "Analogously, lncRNA AB073614 is highly expressed in glioma and indicates a shorter survival time; this lncRNA targets sex-determining region Y-box 7 (SOX7) to enhance the expression of Wnt/β-catenin and promote the proliferation and metastasis of glioma cells." (PMID 35356220, 2022). "AB073614 positively regulated the activity of Wnt/β-catenin signaling pathway and negatively regulated the SOX7 expression level in glioma cells." (PMID 29029454, 2017). "The results showed that the expression of AB073614 was significantly increased in both glioma tissues and cell lines; it was inversely correlated with SOX7 but positively correlated with Wnt/β-catenin signaling activity." (PMID 29029454, 2017). "U251 cells were first transduced with NC, sh-AB073614 or sh-AB073614+sh-SOX7 lentiviral vector to further validate the novel pathway in glioma tissues and cells." (PMID 29029454, 2017). "Of great interest, SOX7 was reported to downregulate Wnt/β-catenin transcription and decrease the expression of Cyclin D1 and c-Myc in glioma." (PMID 29029454, 2017). "The results showed a consistent trend that the inhibitory effect of sh-AB073614 on tumor formation was abolished when SOX7 was deleted, indicating that the tumor-suppressive effect of silencing AB073614 was dependent on the presence of SOX7 in glioma." (PMID 29029454, 2017). "Many studies have demonstrated that SOX7, as a tumor suppressor, is involved in a variety of human cancers, including gliomas." (PMID 29029454, 2017). "Taken together, these results indicated that AB073614 regulated Wnt/β-catenin signaling activity by downregulating SOX7 expression in glioma." (PMID 29029454, 2017). "Western blot showed that SOX7 expression in glioma tissues was lower than that in adjacent normal tissues." (PMID 29029454, 2017). "The findings showed a trend of inverse expression pattern between SOX7 and Wnt/β-catenin signaling pathway in glioma." (PMID 29029454, 2017). "Finally, altered expression of SOX7 has been shown to play a role in the development of different types of gliomas." (PMID 40373085, 2025). "In glioma, the results of a study by Ning Guan suggested that NBAT-1 may up-regulate SOX7 by inhibiting miR-21 to suppress the invasion, migration, and proliferation of glioma cells." (PMID 38243168, 2024). "Finally, altered expression of SOX7 has been shown to play a role in the development of several types of gliomas." (PMID 37790478, 2023). "Finally, the results suggested that AB073614 was an oncogenic lncRNA that promoted the progression of glioma by activating the Wnt/β-catenin signaling pathway via suppression of SOX7." (PMID 29029454, 2017). "Moreover, the inhibition of SOX7 expression significantly reversed the tumor-suppressive effects of silencing AB073614 on glioma cell proliferation, migration, and invasion in vitro." (PMID 29029454, 2017). "Of note, the data showed that the inhibition of SOX7 could reverse the tumor-suppressive effect of the silencing AB073614 on glioma in vitro and in vivo." (PMID 29029454, 2017). "Interestingly, upregulated AB073614 was concomitant with underexpressed SOX7 in both glioma tissues and cell lines." (PMID 29029454, 2017).
glioma (continued). "Therefore, the expression level of SOX7 was examined in both glioma tissues and cells." (PMID 29029454, 2017). "In the same manner, X-inactive specific transcript (XIST) sponges miR-485 in human glioma micro-vascular endothelial cells; hence, the binding of miR-485 enables SRY-box transcription factor 7 (SOX7) to increase the expression level of VEGF." (PMID 37444408, 2023). "However, whether and how SOX7 is regulated by lncRNAs in glioma is still unknown." (PMID 29029454, 2017). "In conclusion, the findings demonstrated that AB073614 promoted the progression of glioma by targeting SOX7 to activate the Wnt/β-catenin signaling pathway, suggesting that the inhibition of AB073614 might be a potential target for therapeutic intervention in glioma patients." (PMID 29029454, 2017).
hepatocellular carcinoma (8 papers, 2014 to 2020). A malignant tumor that arises from hepatocytes. "It has been reported that SOX7 can be regulated by miRNAs in hepatocellular carcinoma and glioblastoma." (PMID 33203802, 2020). "Studies performed on hepatocellular carcinomas (HCCs) revealed that SOX7 regulates the Wnt/β-catenin-signaling pathway via targeting the genes cyclin-1, c-Myc, LEF1 and TCF." (PMID 33152990, 2020). "Molecules modulating SOX7 expression, such as miR-184 in hepatocellular carcinoma (HCC), have also been reported." (PMID 25297608, 2014). "Relationship between SOX7 expression and clinicopathologic features of patients with hepatocellular carcinoma." (PMID 24816720, 2014).
non-small cell lung carcinoma (7 papers, 2014 to 2025). A group of at least three distinct histological types of lung cancer, including non-small cell squamous cell carcinoma, adenocarcinoma, and large cell carcinoma. "SOX7 expression was reported to be silenced in tumor tissues and cell lines in non-small-cell lung cancer in another study, which also showed inhibition of cell growth and promotion of apoptosis after re-expression of SOX7." (PMID 40699642, 2025). "Likewise, inhibition of miR-935 has been shown to increase paclitaxel sensitivity through upregulation of SOX7 in non-small-cell lung cancer." (PMID 35626094, 2022). "In non-small cell lung carcinoma (NSCLC), SOX7 expression is repressed by miR-9, enhancing TGF (Transforming Growth Factor)-β1-induced NSCLC cell invasion and adhesion." (PMID 32111074, 2020). "For example, miR-9 can directly target the 3’UTR of SOX7 and inhibit the transcriptional activity of SOX7 mRNA, thereby promoting TGF-β1-induced non small-cell lung cancer (NSCLC) cell metastasis." (PMID 37369681, 2023).
prostate carcinoma (6 papers, 2009 to 2021). A carcinoma that arises from epithelial cells of the prostate gland. "As SOX7 negatively regulates the Wnt/β-catenin signaling pathway by impeding the transcriptional machinery of β-catenin/TCF/LEF-1, inactivation of SOX7 may be associated with the pathogenesis of cancers, e.g., endometrial cancer and prostate cancer." (PMID 25297608, 2014). "Recent studies of SOX7 in colorectal and prostate cancers showed that levels of this transcription factor were low in these cancers in part due to aberrant DNA methylation of the gene, and the protein behaved as a tumor suppressor gene in these cancers." (PMID 23557216, 2013). "Recently, SOX7 has been proposed to function as a tumor suppressor in colorectal and prostate cancers." (PMID 23557216, 2013). "Interestingly, downregulation of SOX7 in prostate cancer has been found in castration-resistant prostate cancer (CRPC)." (PMID 34067046, 2021). "In prostate cancer tumor-specific promoter hypermethylation of Sox7 was reported." (PMID 19812696, 2009). "However, the role of NFAT1c or SOX7 in regulating PSMA expression in the prostate cancer context is not characterized." (PMID 34067046, 2021). "The gene expression of SOX in human prostate cancer tissue compared with non-cancerous revealed the fact that SOX7, SOX9, and SOX10 were associated with advance-stage prostate cancer, whereas SOX7 and SOX9 were identified as prognostic biomarker in prostate cancer." (PMID 30972102, 2019).
endometrial cancer (5 papers, 2012 to 2017). Primary or metastatic malignant neoplasm involving the endometrium (mucous membrane that lines the endometrial cavity). "In this study, we reported that Sox7, one of Sox transcriptional factors, was frequently underexpressed in endometrial cancer and importantly, it was associated with dysregulation of the Wnt/β-catenin signaling activity." (PMID 23295859, 2012). "The underexpressed Sox7 was associated with increased Wnt/β-catenin signaling activity and high-grade endometrial cancer." (PMID 23295859, 2012). "Sox7 was reportedly downregulated in endometrial cancer showing increased β-catenin, CyclinD1, and fibroblast growth factor 9 (FGF9)." (PMID 26871472, 2016). "Our findings manifest the significance of Sox7 in the pathogenesis and the regulatory mechanisms of aberrant activation of Wnt/β-catenin signaling activity in endometrial cancer." (PMID 23295859, 2012). "As the aberrant activation of Wnt/β-catenin signaling is involved in promoting cancer cell growth, it is of interest to examine the suppressive role of Sox7 in the cell growth capacity of endometrial cancer." (PMID 23295859, 2012). "This indicates that there is a trend of inverse expression pattern between Sox7 and β-catenin in endometrial cancer." (PMID 23295859, 2012). "By real-time quantitative RT-PCR (Q-PCR) analysis, we found that the expression levels of Sox7 in endometrial cancer was 4.2-fold less than normal endometrium (P = 0.005)." (PMID 23295859, 2012). "We noted that some endometrial cancer cases with overexpressed β-catenin were also in concomitant with highly expressed Sox7." (PMID 23295859, 2012). "Taken together, these data further implicate that Sox7 has inhibitory effect on Wnt/β-catenin activity in endometrial cancer cells harboring not only wild-type but also mutant β-catenin." (PMID 23295859, 2012). "Intriguingly, this inhibitory effect of Sox7 on Wnt/β-catenin signaling was not only restricted in wild-type β-catenin endometrial cancer cell line (HEC-1A) but also in mutant β-catenin OEA cells (TOV-112D)." (PMID 23295859, 2012). "This study showed that Sox7 was a potent negative regulator in the Wnt/β-catenin signaling pathway and was frequently underexpressed in endometrial cancer." (PMID 23295859, 2012). "In this study, we identified Sox7, one of the Sox transcription factors family, was significantly down-regulated in high-grade endometrial cancer and inversely correlated with Wnt/β-catenin signaling activity." (PMID 23295859, 2012). "As aberrant activation of Wnt/β-catenin signaling, we thus firstly evaluated the expression status of Sox7 in endometrial carcinoma." (PMID 23295859, 2012). "Enforced expression of Sox7 could remarkably suppress not only Wnt/β-catenin signaling and its downstream oncogenes, but also endometrial cancer cell growth." (PMID 23295859, 2012). "Moreover, we observed that Sox7 expressed mainly in nucleus and partially in cytoplasm of endometrial cancer cells." (PMID 23295859, 2012). "Intriguingly, Sox7 was commonly down-regulated in endometrial cancer samples." (PMID 23295859, 2012). "We also evaluated the expression of Sox7 in human endometrial cancer cell lines by Q-PCR analysis." (PMID 23295859, 2012). "To further investigate the expression status of Sox7 and Wnt/β-catenin activity, we evaluated the expressions of Sox7, β-catenin, CyclinD1 and FGF9 by immunohistochemical analysis on a human endometrial cancer array (EMC1501, Pantomics, Inc)." (PMID 23295859, 2012). "Importantly, we demonstrated that the enforced expression of Sox7 remarkably impeded Wnt/β-catenin signaling mediated cancer cell growth and such suppressive effect was independent on the presence of wild-type or mutant β-catenin in endometrial cancer or OEA cells." (PMID 23295859, 2012). "We firstly examined the localization of Sox7, β-catenin and TCF4 in endometrial cancer cells, HEC-1A." (PMID 23295859, 2012).
endometrial cancer (continued). "Our finding showed that there was a reciprocal relationship between Sox7 and the levels of FGF9 and SFN which were 17.9-fold (P = 0.048) and 7.27-fold (P = 0.008), respectively, higher in endometrial cancer as compared with normal endometrium." (PMID 23295859, 2012). "A previous study showed that SOX7 might be a negative regulator of Wnt/β-catenin signaling pathway through disrupting the transcriptional activity of β-catenin–TCF/LEF complex and its downstream targets, such as Cyclin D1, c-Myc, and FGF9 in endometrial cancer." (PMID 29029454, 2017). "To investigate the suppression effects of Sox7 on Wnt/β-catenin activity of endometrial cancer, we particularly examined the expression levels of CyclinD1 and FGF9 in β-catenin highly expressing endometrial cancer samples which had either with or without expression of Sox7." (PMID 23295859, 2012). "In fact, using endometrial cancer and OEA cells lines as cell models further supported our notion that Sox7 could negatively regulate Wnt/β-catenin signaling activity and its tumorigenic capacities." (PMID 23295859, 2012).
colorectal cancer (4 papers, 2012 to 2025). A primary or metastatic malignant neoplasm that affects the colon or rectum. "For example, SOX7 is downregulated in colorectal cancer, and its low expression correlates with poor prognosis." (PMID 41181151, 2025). "Additionally, SOX7 may be involved in aspirin-mediated growth inhibition of COX2 colorectal cancer cells, in which aspirin may up-regulate the expression of SOX7 by activating the MAPK." (PMID 25297608, 2014). "According to the previous studies, SOX7 mRNA is undetected in some human cancer cell lines including HeLa S3 (cervical cancer), K562 (chronic myelogenous leukemia), SW480 (colorectal cancer), etc., suggesting that SOX7 might be a tumor suppressor gene in these cancers." (PMID 22703285, 2012).
congenital heart defects (4 papers, 2014 to 2025). "Specifically, deletions in the region where SOX7 resides have been demonstrated to simultaneously cause congenital heart defects and intellectual disability." (PMID 40373085, 2025). "TNKS1 is implicated in behavioral anomalies, SOX7 in developmental delay, and GATA4 in concert with SOX7 might cause congenital heart disease." (PMID 25520754, 2014). "Links between SOX7’s role in developmental delay and congenital heart disease have been investigated." (PMID 40373085, 2025). "Links between the role of SOX7 in developmental delay and congenital heart disease have been investigated." (PMID 37790478, 2023). "In other cases, when congenital heart disease was also not observed (Cases 1 to 7), the copy number of genes SOX7 and GATA4 was not changed." (PMID 35327368, 2022).
gastric cancer (4 papers, 2014 to 2023). A primary or metastatic malignant neoplasm involving the stomach. "SOX7 also exhibits tumor-suppressive effects in gastric cancer through potential involvement in abnormalities with the SOX7-associated WNT/β-catenin pathway." (PMID 38132479, 2023).
lung adenocarcinoma (4 papers, 2014 to 2025). A carcinoma that arises from the lung and is characterized by the presence of malignant glandular epithelial cells. "The reduced SOX7 expression was correlated with multiple poor prognostic indicators of patients with lung adenocarcinoma." (PMID 28266181, 2017). "However, ACTA2-AS1 may act as a tumor suppressor in lung adenocarcinoma and liver cancer cell via sequestering miR-378a-3p and miR-4428 to upregulate the expression of SOX7." (PMID 33845844, 2021).
acute myeloid leukemia (3 papers, 2016 to 2024). Acute myeloid leukemia (AML) is a group of neoplasms arising from precursor cells committed to the myeloid cell-line differentiation. "Through antagonizing the Wnt/β-catenin signaling pathway, SOX7 inhibits the proliferation of acute myeloid leukemia (AML) and CRC." (PMID 38331879, 2024). "A recent study has also revealed a tumor suppressor role for SOX7 in acute myeloid leukemia (AML)." (PMID 29029405, 2017). "Consistently, a latest study in acute myeloid leukemia (AML) also indicated SOX7 to have a negative modulatory effect on the Wnt/beta-catenin pathway." (PMID 27188720, 2016). "This analysis revealed that SOX7 expression levels were frequently and significantly higher in childhood and adult BCP-ALL when compared to normal bone marrow and other types of leukemia, including T-ALL, acute myeloid leukemia (AML), chronic leukemias and myelodysplastic syndrome (MDS)." (PMID 29029405, 2017).
glioblastoma (3 papers, 2018 to 2020). The most malignant astrocytic tumor (WHO grade IV). "MiR-24 was found to be significantly associated with survival of patients with glioblastoma (GBM) multiforme, and promoted GBM progression by targeting tumor suppressor sex-determining region Y-box 7 (SOX7)." (PMID 33123467, 2020).
myelodysplastic syndrome (3 papers, 2017 to 2020). A clonal hematopoietic disorder characterized by dysplasia and ineffective hematopoiesis in one or more of the hematopoietic cell lines. "Consistently, low SOX7 expression correlated with poor prognoses in patients with lung cancer and myelodysplastic syndrome." (PMID 29757932, 2018).
autism (2 papers, 2023 to 2025). Persistent deficits in social interaction and communication and interaction as well as a markedly restricted repertoire of activity and interest as well as repetitive patterns of behavior. "The strong LD in SOX7 and the powerful AT method warrant our identification of the autism-associated gene SOX7." (PMID 37790478, 2023). "Another study also found that differential methylation was associated with an “elevated polygenic burden” for autism and further identified that two significantly associated CpG sites were located near GWAS markers for autism on chromosome 8 in the same region as SOX7." (PMID 37790478, 2023). "Additionally, the association of SOX7 with autism has been investigated directly." (PMID 37790478, 2023). "The successful replications of SOX7 in the replication data, gene expression data, and the associated biological plausibility underscores the robustness of the finding of the connection between SOX7 and autism." (PMID 37790478, 2023). "A GWAS performed in a Mexican population found that SOX7 was differentially methylated between autism cases and controls." (PMID 37790478, 2023). "The expression of SOX7 is increased in autism patients relative to controls by a multiplicative factor of 2.25." (PMID 37790478, 2023).
bladder cancer (2 papers, 2018 to 2024). "Therefore, SOX7 and CYGB may play an important role in the progression of bladder cancer, and they can be used as prognostic markers of bladder cancer patients." (PMID 39227479, 2024).
colon carcinoma (2 papers, 2018 to 2025). "One of the most important findings was the downregulation of nuclear SOX7 in tumor tissue compared to non-malignant lung samples, in alignment with previous reports implicating SOX7 as a tumor suppressor in various cancers, including lung, breast, and colon carcinomas." (PMID 41373817, 2025).
congenital diaphragmatic hernia (2 papers, 2019 to 2024). A posterolateral defect of the diaphragm that allows passage of abdominal viscera into the thorax, leading to respiratory insufficiency and persistent pulmonary hypertension with high mortality. "The presence of SOX7 haploinsufficiency has been associated with the occurrence of cardiac defects and congenital diaphragmatic hernias." (PMID 38352102, 2024). "SOX7 haploinsufficiency has been linked to cardiac defects and congenital diaphragmatic hernia, and is characterized by microdeletions at 8p23.1 that include the Sox7 gene." (PMID 30984768, 2019).
liver cancer (2 papers, 2021 to 2023). An epithelial or non-epithelial malignant neoplasm that arises from the liver.